RN7SL587P (RNA, 7SL, cytoplasmic 587, pseudogene)
Gene: Miscellaneous RNA gene on chromosome 14 (77,547,566 to 77,547,846, reverse strand). Ensembl gene ENSG00000240233.
Homologues: Orthologues: chimpanzee Metazoa_SRP (99% identical), macaque Metazoa_SRP (94% identical). Paralogues in human: RN7SL1 (86% identical), RN7SL2 (86% identical), RN7SL3 (85% identical), RN7SL126P (82% identical), RN7SL444P (82% identical), RN7SL45P (82% identical), RN7SL709P (82% identical), RN7SL712P (82% identical), RN7SL769P (82% identical), RN7SL7P (82% identical), RN7SL336P (82% identical), RN7SL493P (82% identical), and 705 more.